STAB1 (stabilin 1)
Diseases named in the same sentence as STAB1 in open-access papers (continued):
Sharing a sentence is not in itself a finding about the gene and the disease.
cancer (32 papers, 2015 to 2025). A tumor composed of atypical neoplastic, often pleomorphic cells that invade other tissues. "In cancer, STAB1 has been implicated in facilitating cancer cell adhesion, transmigration, growth, and metastasis." (PMID 41007347, 2025). "Stabilin-1 (STAB1), a scavenger receptor linked to cellular trafficking, inflammation, and cancer, exerts protective anti-infective effects by modulating cytokine/chemokine production and immune cell recruitment." (PMID 41035636, 2025). "Another example is the STAB1 (stabilin 1) gene, whose expression levels are associated with survival in several cancer types, including breast cancer." (PMID 36109686, 2023). "CLEVER-1 or stabilin 1 has been historically linked to cancer proliferation and spread as noted in Stab1 knockout mice." (PMID 36031601, 2022). "Strong association of stabilin-1+ TAMs with worse prognosis was shown in several human cancers." (PMID 36686729, 2022). "Thus, STAB1 exhibits multifunctional mechanisms to maintain tissue homeostasis, and the loss of STAB1 can be detrimental to tissue repair, leading to altered immune responses and disease progression, including cancer." (PMID 41007347, 2025). "The role of STAB1 in cancer progression and metastasis first became evident in Stab1 knockout (KO) mice, which developed smaller primary tumors and metastatic foci for some cancers." (PMID 41007347, 2025). "Elevated expression of STAB1 on TAMs correlates with poor prognosis in several cancers, including breast, gastric, bladder, and CRC." (PMID 41007347, 2025). "One key finding was upregulation of STAB1 in macrophages after carboplatin and paclitaxel, drugs that are widely used in treatment of cancers." (PMID 39578450, 2024). "Even in cancer development, this is relevant, as Stab1 recruits both immunosuppressive macrophages and regulatory T cells (Treg)." (PMID 38275881, 2024). "Most recently, we reported that stabilin-1 mediates the clearance of the most potent growth factor that supports the proliferation of cancer cells, EGF." (PMID 39516356, 2024). "The inhibition of Stab1 is evaluated in a phase 1/2 clinical trial as adjuvant cancer immunotherapy." (PMID 38946049, 2024). "STAB1 targeting is also currently investigated in an early-phase clinical cancer trial (NCT03733990)." (PMID 34817749, 2022). "Stabilin-1 (STAB-1) is a scavenger receptor involved in cell trafficking, inflammation, and cancer; however, its role in infection remains to be elucidated." (PMID 34374322, 2021). "These PSRs including BAI1, CD300e, Stabilin-1 and others are worth considering in the context of anti-cancer immune therapy." (PMID 32087708, 2020). "Silent clearance function of stabilin-1 makes it an attractive candidate for delivery of immunomodulatory anti-cancer therapeutic drugs to TAM." (PMID 27105498, 2016). "Thus, understanding the role of STAB1 in cancer progression is of clinical importance and can contribute to the development of new anti-cancer therapeutics." (PMID 41007347, 2025). "Moreover, human trials using anti-STAB1 antibody treatment indicate a shift towards immune activation and the potential to overcome cancer treatment resistance experienced with other immunotherapies." (PMID 41007347, 2025). "Besides promoting lymphatic metastasis, STAB1 also facilitates the adherence of cancer cells to endothelial venules in the bloodstream." (PMID 41007347, 2025). "Thus, targeting STAB1 offers a novel strategy for cancer immunotherapy by modulating TAM-mediated immune suppression and enhancing T-cell-mediated antitumor activity." (PMID 41007347, 2025). "In summary, stabilin-1 has a highly complex function in cancer." (PMID 36686729, 2022). "In TNBC with STAB1 overexpression, there seems to be a dysfunction of CD8 + lymphocytes and in some cancers, which are STAB1 high, CD8 + lymphocytes have correlated with a worse prognosis, whereas in cancers with low STAB1, they have correlated with a good prognosis." (PMID 35917053, 2022).
cancer (continued). "Most studies suggested that STAB1 was an oncogene and up‐regulated in many cancers." (PMID 32027093, 2020). "Furthermore, we discuss how targeting Stabilin-1 may represent a potential therapeutic approach for limiting cancer development and advancement." (PMID 41007347, 2025). "Increased amounts of specific TAM subsets identified by CD163, CD206, stabilin-1, and TREM2 biomarkers correlate with both hematogenous and lymphatic metastasis in all cancer types studied." (PMID 39516356, 2024). "STAB1, TM4SF1, and TNS3 are involved in cell adhesion and motility, which are relevant to cancer metastasis and invasion, however, their roles in interaction between leukemic stem cells and bone marrow niche deserve further investigation." (PMID 26517675, 2015). "STAB1, EIF4G1, and PLOD3 have been reported to regulate the proliferation, migration, and invasion of cancer cells; however, the role of FAM208A in cancer is unclear." (PMID 37373553, 2023). "In cancer patients, number of TAM-expressed SRs (CD204, MARCO, CD68, LOX-1, Dectin-1, CD206, CXCL16, Stabilin-1, CD163, and RAGE) associates with negative and more sever prognosis." (PMID 36686729, 2022). "In addition, we found significant downregulation of multiple cancer-related genes coding for cytochrome P450 1B1 (CYP1B1), C-C chemokine receptor type 2 (CCR2), stabilin-1 (STAB1) and transmembrane protein 176B (TMEM176B)." (PMID 32780768, 2020). "Therefore, the observed downregulation of both, STAB1 and TMEM176B may highlight novel players in the anti-cancer activity of metformin." (PMID 32780768, 2020). "Among them, many international cohorts of cancer patients have shown negative prognostic value for TAMs expressing CD68, CD163, CD204, CD206, MARCO, and stabilin-1." (PMID 39516356, 2024).
infection (7 papers, 2021 to 2025). The state of being infected such as from the introduction of a foreign agent such as serum, vaccine, antigenic substance or organism. "Together, these results indicate that infection by pathogenic Listeria induces a downregulation of STAB-1 expression in infected cells and tissues." (PMID 34374322, 2021). "In addition, whereas STAB-1 appears to promote bacterial uptake by macrophages, infection by pathogenic Listeria induces the down regulation of STAB-1 expression and its delocalization from the host cell membrane." (PMID 34374322, 2021). "Stab1 was present in the endothelium and monocytes/macrophages before infection and 1d and 2d OM, but only in the endothelium at 6 h." (PMID 36092940, 2022). "We used this experimental model to confirm the involvement of STAB-1 in the recruitment of innate immune cells to the infection site." (PMID 34374322, 2021). "This suggests an active mechanism driven by Lm virulence factors to control STAB-1 expression/localization, diminish host protective responses, and promote infection." (PMID 34374322, 2021). "Altogether, these results indicate that, in vivo, STAB-1 potentiates the recruitment of immune cells to the infection site upon an inflammatory stimulus." (PMID 34374322, 2021). "Altogether, these results indicate a role for STAB-1 in the recruitment of immune cells to Lm-infection sites possibly through the expression control of attracting chemokines." (PMID 34374322, 2021). "Using a mouse model of infection, we demonstrate here that STAB-1 controls Lm-induced cytokine and chemokine production and immune cell accumulation in Lm-infected organs." (PMID 34374322, 2021). "We demonstrate that, during an infection by Listeria monocytogenes (Lm), STAB-1 is not only required for bacterial uptake by macrophages but also for an efficient inflammatory response, immune cell accumulation, and early myeloid cells recruitment to the infection site." (PMID 34374322, 2021). "We propose STAB-1 as a new SR involved in the control of Lm infection through the regulation of host defense mechanisms, a process that would be targeted by bacterial virulence factors to promote infection." (PMID 34374322, 2021). "In addition, by microscopy, we also observed a de-localization of STAB-1 from the host cell membrane upon infection." (PMID 34374322, 2021). "Interestingly, we also show that infection by pathogenic Listeria induces the downregulation of STAB-1 expression and its de-localization from the cell membrane, suggesting a bacterial active virulence process targeting STAB-1 aiming to promote infection." (PMID 34374322, 2021). "Here, we show that infected STAB-1 KO mice produced reduced serum, liver and splenic levels of IL-6 and TNF-α as compared to WT mice, suggesting that STAB-1 participates in the regulation of the inflammatory cytokine response in Lm-targeted mouse organs upon infection." (PMID 34374322, 2021). "STAB-1 could be required for the proper migration, position, and function of other immune cells, in particular CD8α+ dendritic cells of the splenic marginal zone that were shown to be an obligate cellular entry point for a productive infection by Lm." (PMID 34374322, 2021). "In the absence of infection, spleens of WT and STAB-1 KO mice showed comparable myeloid cell populations." (PMID 34374322, 2021). "The scavenger receptor gene Stab1 was not upregulated by 4T1, but was decreased by infection." (PMID 40547518, 2025). "Nevertheless, impaired control of the infection by STAB-1 KO mice may not be only due to reduced myeloid cell recruitment to the sites of infection." (PMID 34374322, 2021). "Importantly, this reduction of the cytokine levels between WT and STAB-1 KO mice is not observed in absence of infection." (PMID 34374322, 2021).
infection (continued). "We found three genes that were commonly activated with infection with SCV2 at both 12 and 24 hpi (DUSP1, HES1, KLF2) and some non-congruent genes at 12 hpi (CCL5, ZBP1, NRXN2, STAB1, SLC25A47, CXCL11) and 24 hpi (FOXA2, RHOB)." (PMID 37504520, 2023).
STAB1 also shares sentences with these, for which no sentence is quoted: lymphoma (3 papers); acute myelogenous leukemia (2); Alzheimer disease (2); bipolar disorder (2); Listeria infection (2); liver cancer (2); arteriosclerosis (1); B-cell lymphoma (1); bacterial infection (1); brain disorder (1); cervical cancer (1); cognitive decline (1); colon carcinoma (1); depression (1); Ecchymosis (1); gastrointestinal stromal tumor (1); Lipedema (1); lung adenocarcinoma (1); lupus nephritis (1); Lymphadenopathy (1); Lynch syndrome (1); malaria (1); myeloid malignancies (1); myeloproliferative disease (1); myocarditis (1); neurodegenerative disease (1); neurodevelopmental disorder (1); Pancreatic Cancer (1); pancreatic insulinoma (1); peritoneal disease (1).
A further 9 diseases each share a sentence with STAB1 in 1 paper.